RN7SL39P (RNA, 7SL, cytoplasmic 39, pseudogene)
Gene: Miscellaneous RNA gene on chromosome 18 (3,571,215 to 3,571,511, reverse strand). Ensembl gene ENSG00000241223.
Homologues: Orthologues: chimpanzee Metazoa_SRP (97% identical), macaque Metazoa_SRP (91% identical). Paralogues in human: RN7SL1 (79% identical), RN7SL2 (79% identical), RN7SL296P (79% identical), RN7SL187P (77% identical), RN7SL3 (77% identical), RN7SL479P (77% identical), RN7SL444P (77% identical), RN7SL732P (77% identical), RN7SL7P (77% identical), RN7SL322P (77% identical), RN7SL664P (77% identical), RN7SL45P (76% identical), and 705 more.